JAK2 (Janus kinase 2)
Diseases named in the same sentence as JAK2 in open-access papers (continued):
Sharing a sentence is not in itself a finding about the gene and the disease.
osteosarcoma (continued). "Our results demonstrated that resveratrol inhibited osteosarcoma cell proliferation and tumorigenesis ability, which was correlated with cytokines inhibition related JAK2/STAT3 signaling blockage." (PMID 30356255, 2018). "In renal cell carcinoma and osteosarcoma, ginkgetin induced cell apoptosis through JAK2/STAT3 signaling." (PMID 29190983, 2017). "UMR-106 osteosarcoma cells express a GH-responsive JAK2/STAT5 signaling pathway, providing an experimental model to study the influence of statins on this system." (PMID 24489959, 2014). "A recent study suggested that the UMR-106 osteoblast-like osteosarcoma cell line expresses a GH-responsive Jak2/STAT5 signaling system." (PMID 23071812, 2012). "According to a recent study, the osteoblast-like osteosarcoma cell line UMR 106 expresses a GH-responsive Jak2/STAT5 signaling system." (PMID 23071812, 2012). "In addition, inhibition of JAK2/STAT3 signaling led to a decrease in the osteosarcoma stem cell marker CD133." (PMID 39206407, 2024). "Taken together, we indicated that FANCD2 may mediate ferroptosis in osteosarcoma by JAK2/STAT3 pathway to regulate tumor cell growth." (PMID 36814203, 2023). "Based on previous research, we speculated that FANCD2 interacts with JAK2/STAT3 pathway to mediate osteosarcoma development." (PMID 36814203, 2023). "In addition, BMSC-derived exosomes carrying proteins, such as LCP1, stimulated osteosarcoma metastasis via the LCP1-induced activation of the JAK2/STAT3 signaling pathway." (PMID 37377390, 2023). "Moreover, miR-331-3p affected the occurrence and development of osteosarcoma by targeting the SOCS1/JAK2/STAT3 signaling pathway." (PMID 36199788, 2022). "The inhibitory effects of ML264 on osteosarcoma cells are likely mediated via inhibition of JAK2 and STAT3 phosphorylation, decrease in β‐catenin and Runx2 levels, down‐regulation of cyclin D1, cyclin E1, CDK4, N‐cadherin, vimentin, Snail and MMPs expression, and up‐regulation of E‐cadherin levels." (PMID 32285603, 2020). "JAK2/STAT3 blockage by resveratrol will provide a valuable strategy for osteosarcoma therapy." (PMID 30356255, 2018). "This study investigated whether 4-MD can mediate its anti-proliferative and apoptotic effects in human osteosarcoma cells through the suppression of the JAK2/STAT3 pathway." (PMID 26755649, 2016). "Several studies have shown that deguelin effectively inhibited the migration and invasion of triple negative breast cancer and human osteosarcoma cells by downregulating MMP-2 and Janus kinase 2 (JAK2)/STAT3 signaling pathways." (PMID 40672375, 2025). "In osteosarcoma, DLGAP5 has been demonstrated to promote tumor development via the IL-6/JAK2/STAT3 signaling pathway." (PMID 40181976, 2025). "It has been shown that DLGAP5 can activate interleukin-6/Janus kinase 2/signal transducer and activator of transcription 3 (IL-6/JAK2/STAT3) signaling pathway thereby promoting the proliferation and invasion of osteosarcoma cells." (PMID 36712920, 2023). "Exosomes have been shown to regulate the development of osteosarcoma as part of drug delivery, and can positively affect osteosarcoma through signaling pathways such as Wnt/β-catenin, ERK1/2, and JAK2/STAT3." (PMID 36678850, 2023). "By interacting with DNMTs, THAP9-AS1 modulates methylation patterns in the SOCS3 promoter region, paving the way for JAK2/STAT3 pathway activation and, consequently, osteosarcoma progression." (PMID 38140058, 2023). "DLGAP5 has been shown to activate the IL-6/JAK2/STAT3 signaling pathway, thereby promoting the proliferation and invasion of osteosarcoma cells." (PMID 37958803, 2023). "Another curcumin analogue, L48H37, also decreased the phosphorylation of JAK1, JAK2, JAK3, and STAT3 in osteosarcoma cells." (PMID 34867402, 2021). "In conclusion, ML264 inhibited the JAK2/STAT3 and Wnt/β‐catenin signalling pathways via down‐regulation of KLF5 and EGR1 expression, thereby inhibiting proliferation and metastasis of osteosarcoma cells." (PMID 32285603, 2020).
osteosarcoma (continued). "Simvastatin was shown to suppress phosphorylation of JAK2 and STAT3 in two human renal cell carcinoma cell lines in a nude mouse model and growth hormone-stimulated JAK2 and STAT5 activation in osteosarcoma cells." (PMID 30116531, 2018). "Kinase targets found in the analysis were for osteosarcoma (KIT), Ewing’s sarcoma (ALK), undifferentiated pleomorphic sarcoma (JAK2, ABL2), alveolar rhabdomyosarcoma (NTRK1), and leiomyosarcoma (ALK)." (PMID 29541442, 2018). "Meanwhile, PI3K/AKT/NF-κB signaling, a downstream pathway of JAK2/STAT3, was also examined in the gradient of resveratrol treated osteosarcoma cells." (PMID 30356255, 2018). "4-MD inhibited phosphorylation of JAK2 and STAT3 with the inactivation of mitogen-activated protein kinases (MAPKs) and CREB, and the upregulation of PTEN in osteosarcoma cells." (PMID 26755649, 2016). "OSM activates JAK2 and STAT3 upon binding to its receptor in many cells including murine, rat, and human osteoblastic cells and osteosarcoma cell lines." (PMID 21481226, 2011). "We treated osteosarcoma cell lines with anti-tumor agent and some specific inhibitors including ERK inhibitor, HIF1-α inhibitor, JAK2 inhibitor, LY294002, and others but we were unable to inhibit EGR1 expression effectively." (PMID 21283769, 2011). "Recent studies on osteosarcoma involving the LCP1 gene (also known as actin-bundling protein L-plastin or LPL), have shown that the aberrant expression of LCP1 gene activates the JAK2/STAT3 signaling pathway, linking IL-6, IL-6R, and LCP1 in the context of tumor progression." (PMID 40759647, 2025). "It had been demonstrated that the inhibition of JAK2/STAT3 signaling pathway could decrease cell viability, invasion and migration of osteosarcoma cells and induced apoptosis in cancer cells." (PMID 38420199, 2024). "It has been reported that lymphocyte cytoplasmic protein 1 (LCP1) in BMSC-Exos promotes the progression of osteosarcoma through the JAK2/STAT3 pathway, suggesting that targeting LCP1 may provide a means to treat osteosarcoma." (PMID 36678850, 2023). "Similarly, inhibition of JAK2, which is downstream of IL4R, delayed tumor growth in an osteosarcoma xenograft model." (PMID 33419470, 2021). "Furthermore, induction of JAK2/STAT3 axis by exosomal LCP1 leads to carcinogenesis and migration of osteosarcoma cells." (PMID 34769099, 2021). "Furthermore, in 80 osteosarcoma patients, the mean expressions of p-JAK2 and STAT3 in primary osteosarcoma tissues with lung metastasis (9.23 and 14.82, respectively) are much higher than those without lung metastasis (2.43 and 5.06, respectively), and a positive correlation is evident between both." (PMID 36923933, 2023). "In addition, JAK2 and STAT3 expression were reduced by silencing of FANCD2, and STAT3 activator (colivelin) distinctly reversed tumor suppressor effects of FANCD2 silencing on osteosarcoma development." (PMID 36814203, 2023). "However, it is unclear on the relationship between JAK2/STAT3 pathway and FANCD2 in osteosarcoma." (PMID 36814203, 2023). "The osteosarcoma, proliferation, and immune escape through the JAK2–STAT3–PD–L1-signaling axis can all be inhibited by the liposomal form of QUE by inhibiting JAK2 through the JH2 domain in a non-covalent way." (PMID 37376104, 2023). "In both cell lines, phosphorylated JAK2 and STAT3 was decreased while phosphatase SHP1, a negative regulator of STAT3, was upregulated, indicating that BD reversed the constitutive activation of the JAK2/STAT3 signaling pathway in the osteosarcoma cell lines." (PMID 36046775, 2020).
Thrombocytopenia (60 papers, 2010 to 2025). A reduction in the number of circulating thrombocytes. "Technical success was found to be predicted by the existence of the JAK2 V617F mutation both in the short and long term, despite the observation of certain problems, such as heparin-induced thrombocytopenia." (PMID 39219865, 2024). "More recently, pacritinib (a JAK2 inhibitor) was approved for patients with intermediate- or high-risk MF and severe thrombocytopenia (platelet count <50 × 109/L)." (PMID 37345196, 2023). "It is also important to note that all three patients were treated with HU, as cyclic thrombocytopenia has been described in a 66-year-old male with a 9-year history of PV associated with the JAK2 mutation." (PMID 34681577, 2021). "This case indicates that thrombocytopenia and increased JAK2 gene copies may be risk factors for poor prognosis after ICI and RT treatment." (PMID 38974233, 2024). "In this study, we found that JAK2 downregulation is highly associated with CIT, which may stress the importance of JAK2 in thrombocytopenia-related diseases." (PMID 35682967, 2022). "For this reason, we hypothesized that carboplatin might mainly influence the hematopoiesis in earlier stage since prominent JAK2 downregulation-associated thrombocytopenia is found in our study both in vivo and in vitro." (PMID 35682967, 2022). "That is, recurrent thrombocytopenia and increased JAK2 copy number are indicative of a poor prognosis." (PMID 38974233, 2024). "Thrombocytopenia, which is mentioned as an adverse effect of ruxolitinib, has also been controversial as having a negative regulatory role of JAK2 in thrombopoiesis at the end of megakaryocyte differentiation was suggested." (PMID 34445192, 2021). "Recurrent thrombocytopenia may activate the JAK2/STAT3 pathway, leading to megakaryocyte differentiation and platelet biogenesis." (PMID 38974233, 2024). "Prospective studies are needed to demonstrate any modifications of the JAK2/STAT3 pathway following thrombocytopenia and to determine whether the JAK2/STAT3 pathway may contribute to hyperprogression." (PMID 38974233, 2024). "Whether other different TRAs can exert therapeutic effect on carboplatin-induced thrombocytopenia through mechanism other than reactivating JAK2/STAT3 pathway needs further investigation in the future." (PMID 35682967, 2022). "Several JAK2 inhibitors are in clinical development, which could prove beneficial in patients with anemia and/or thrombocytopenia." (PMID 35215273, 2022). "Such is the case with the prominent JAK2 inhibitor Ruxolitinib, which proved to be temporarily effective in early stages of clinical trials, yet later it induced resistance mechanisms and various side effects like thrombocytopenia and reactivation of opportunistic infections." (PMID 41031165, 2025). "Our findings establish CCR5 as a therapeutic target for thrombocytopenia and identify miltefosine as a CCR5 agonist that promotes MK differentiation and platelet production via MAPK and JAK2/STAT3 signaling." (PMID 40292315, 2025). "By demonstrating that miltefosine, a CCR5 agonist, promotes MK differentiation and platelet formation through activation of MAPK and JAK2/STAT signaling, we unveil a therapeutic axis for thrombocytopenia." (PMID 40292315, 2025). "Regarding thrombocytopenia, CALR-mutant patients had the lowest cumulative incidence compared to JAK2- and MPL-mutant patients and “triple negative” (p = 0.001) patients." (PMID 37444441, 2023). "Pacritinib is a JAK2/FLT3 inhibitor with milder myelosuppressive properties and favorable results in patients with thrombocytopenia." (PMID 35215273, 2022).
Thrombocytopenia (continued). "Upon complete deletion of Mpl, Jak2-V617F expression did not increase platelet numbers: Mpl−/−;Jak2V617F/+ mice displayed thrombocytopenia and low numbers of Mk and MkP typical of Mpl−/− mice." (PMID 38491305, 2024). "This is especially evident in states of thrombocytopenia where thrombopoietin stimulates its receptor on the surface of platelets, the myeloproliferative leukemia protein (MLP), inducing its dimerization and activation of janus kinase 2 (JAK2)." (PMID 35328719, 2022). "Elevated platelet numbers in murine models of carboplatin-induced thrombocytopenia suggested that JAK2-STATs and/or TPO-dependent signaling might be involved in D-dencichine treatment of thrombocytopenia." (PMID 29666579, 2018). "In addition to the intrinsically increased number of JAK2 copies, recurrent thrombocytopenia and TPO application might activate the JAK2/STAT3 signaling pathway as a feedback mechanism to stimulate thrombopoiesis." (PMID 38974233, 2024). "JAK2 deficient could be barely seen among humans, which may be due to the fact that JAK2 deficiency is lethal in early life, and downregulation of JAK2 is mainly mentioned in the therapy for MPD, in which thrombocytopenia becomes a dose-limited factor to the use of JAK2 inhibitors." (PMID 35682967, 2022). "Without the reactivation of JAK2/STAT3 pathway, TPO is unlikely to be effective enough to treat carboplatin-induced thrombocytopenia." (PMID 35682967, 2022). "Moreover, elevated JAK2 copy number and aberrant activation of the JAK2/STAT3 pathway, which are negative feedback pathways for thrombocytopenia, contribute to platelet biogenesis and immune escape." (PMID 38974233, 2024).
lymphoma (56 papers, 2010 to 2025). A malignant (clonal) proliferation of B- lymphocytes or T- lymphocytes which involves the lymph nodes, bone marrow and/or extranodal sites. "To specifically address the functional implications of JAK2 signaling disruption on lymphoma cell susceptibility to ADCP we generated JAK2 deficient lymphoma target cells." (PMID 32824276, 2020). "Although activating point mutations of JAK2, which are common in myeloid neoplasms, are very rarely found in lymphomas, the enhanced activity of the JAK/STAT signaling pathway by 9p24 amplification seems to play an important role in the development of cHL as our own data and other studies suggest." (PMID 33567641, 2021). "Extensive research has identified small molecule compounds, including the organosilicon compound DCZ0858 and the JAK2 inhibitor TG101209, as agents capable of exerting anti-lymphoma effects by modulating the JAK2/STAT3 signaling pathway." (PMID 40051568, 2025). "This amplification leads to increased expression of PD-L1, PD-L2, and JAK2, enhancing the sensitivity of these lymphomas to immune checkpoint inhibitors targeting the PD-1/PD-L1 pathway, thereby offering significant therapeutic potential." (PMID 40299829, 2025). "A prime example can be found in hematological malignancies, such as ALL, lymphoma, and MPNs, genetic alterations affecting JAK2 are frequently observed." (PMID 41438753, 2025). "The suppression of cell proliferation in LMP1-expressed lymphoma cells by JAK2 inhibitors, along with the enhancement of chemotherapeutic cytotoxicity, was shown to be a promising strategy in treating EBV-related lymphomas." (PMID 38675906, 2024). "In conclusion, we have shown that inhibition of JAK2 facilitates an increased macrophage-mediated lymphoma cell depletion in vitro, with superior overall survival of hMB JAK2−/− transplanted NSG mice in vivo." (PMID 32824276, 2020). "It is thought that impaired SOCS1-mediated JAK2 degradation results in sustained JAK2 activation and low turnover of JAK2 protein leading to lymphomas." (PMID 24757565, 2014). "However, very few studies have been conducted to evaluate the efficacy of JAK2 inhibitors in anti-Burkitt lymphoma and inducing the lymphoma cells differentiation." (PMID 34588425, 2021). "We also confirm that a subset of refractory, PD-L1 positive lymphomas may harbor genetic alterations of 9p21.4 amplicon affecting PD-L1, PD-L1 and JAK2 genes." (PMID 27861596, 2016). "Whether or not JAK2 inhibitors are effective against acute leukemia or lymphoma caused by this fusion remains to be determined." (PMID 35472244, 2022). "In contrast, JAK2 may also play some role in preventing the growth of lymphomas." (PMID 34948183, 2021). "Some data have confirmed that the expression of JAK2 is abnormally increased in approximately 30% of Hodgkin’s lymphoma (HL) and 30–50% of primary mediastinal large B-cell lymphoma (PMBCL), suggesting that the abnormal activation of JAK2 is associated with the development of lymphoma." (PMID 34588425, 2021). "The majority of distinct CNVs we observed were hallmarks of the respective lymphoma subtype, e.g., 8q and 11q deletions in the T-PLL, a 13q14 deletion in the case 5 CLL, and the gains of JAK2/PD-L1/PD-L2 and REL in the HL of cases 1 and 4, respectively." (PMID 40404986, 2025). "While M2-targeted therapeutic strategies may be appropriate for acute leukemias, lymphomas, and MM where M2 macrophages drive pathology, our findings suggest that therapeutic approaches targeting the inflammatory axis may be more relevant in JAK2-positive MPNs." (PMID 41239536, 2025). "As this lymphoma is highly dependent on the constitutive activation of STAT3, 5-AZA impaired PEL cell survival, and when used in combination with AG490 JAK2/STAT3 inhibitor, it potentiated its cytotoxic effect." (PMID 38534772, 2024). "In lymphomas, there is evidence of DNA hypermethylation affecting the SOCS1 gene, which in turn can promote cell proliferation by enhancing JAK2 activity." (PMID 37664523, 2023).